INS (insulin)
Diseases named in the same sentence as INS in open-access papers (continued):
Sharing a sentence is not in itself a finding about the gene and the disease.
Insulin resistance (continued). "Pregnancy is associated with insulin resistance and increased insulin demand whereas lactation results in improved insulin action." (PMID 24236022, 2013). "Insulin resistance is implicated in several potential adverse metabolic changes, including disturbances in insulin and glucose metabolism, which can affect energy supply and blood flow." (PMID 23777457, 2013). "Given that patients with T2DM usually have hyperlipidemia, which can cause insulin resistance and decreased insulin secretion, our second aim was to investigate the effect of palmitic acid on the expression of 5-HT2CR in pancreatic β-cells." (PMID 23349838, 2013). "As insulin resistance is considered a central mechanism in the causation of type 2 diabetes, we performed similar models of progressive adjustment, but adding insulin prior to adiponectin and inflammation markers." (PMID 23806173, 2013). "Chronic administration of the mTOR inhibitor rapamycin has been shown to substantially impair glucose tolerance and insulin action, inducing muscle insulin resistance despite weight loss in rats." (PMID 23822543, 2013). "Shift work can be either protective against, or a risk factor for, insulin resistance in humans, and circadian rhythm can cause day vs. night changes in insulin sensitivity." (PMID 24133483, 2013). "Secreted cytokines, such as TNF-α and IL-1β, can directly inhibit insulin secretion as well as insulin signaling, and cause insulin resistance." (PMID 24064574, 2013). "High insulin concentrations and insulin resistance were associated with low iron and vitamin E concentrations and the vitamin E:lipids ratio (p < 0.05)." (PMID 24335710, 2013). "The extent of the reductions seen with adiponectin and inflammation markers was nearly as large as that seen with fasting insulin, a surrogate measure of insulin resistance, which is recognized as a major proximal cause of type 2 diabetes." (PMID 23806173, 2013). "Low adiponectin has been repeatedly associated with insulin resistance, consistent with the known insulin-sensitizing bioactivity of the protein." (PMID 24349098, 2013). "The absolute deficiency of insulin and insulin resistance are the basic pathophysiologic changes of type 1 and type 2 diabetes, respectively." (PMID 24386004, 2013). "In general, our observations seem to be in line with data which investigated insulin resistance during pregnancy and its association with insulin therapy and beta cell dysfunction during pregnancy." (PMID 23819910, 2013). "T2DM is a metabolic condition characterised by insulin resistance causing reduced responsiveness to the effect of insulin on peripheral tissues, resulting in high blood sugar levels." (PMID 24236071, 2013). "Several studies reported that a decrease in insulin secretion and insulin resistance induced by hyperglycemia has been associated with decreased Akt activity." (PMID 24324490, 2013). "Nicotine is an important ingredient in cigarette smoke that can cause insulin resistance by affecting insulin action." (PMID 23922856, 2013). "Taken together, this study identifies the phosphatase DEP-1 as novel component in insulin signaling, and molecular target for the treatment of insulin resistance and obesity-associated diseases." (PMID 23889985, 2013). "Magnesium plays a role in glucose and insulin homeostasis and evidence suggests that magnesium intake is associated with insulin resistance (IR)." (PMID 23472169, 2013). "Further, most of the adiponectin knockout mice were more insulin resistant than controls, although to different degrees, and this factor has been associated with hepatic insulin resistance." (PMID 23762871, 2013). "In contrast, LPS and glucose combined caused marked glucose intolerance and insulin resistance and significantly impaired pancreatic insulin secretion." (PMID 23826335, 2013). "Insulin increases apelin synthesis in adipocytes and plasma apelin level rises in obesity associated with insulin resistance." (PMID 23691290, 2013).
Insulin resistance (continued). "Leptin has been implicated in causing peripheral insulin resistance by attenuating insulin action, and perhaps insulin signaling, in various insulin-responsive cell types." (PMID 23634778, 2013). "Endothelial dysfunction per se can even contribute to insulin resistance, since impaired microvascular vasodilation in skeletal muscle reduces delivery of insulin and glucose to skeletal muscle and thereby causes insulin resistance." (PMID 23691262, 2013). "Smoking reduces insulin sensitivity or induces insulin resistance and enhances cardiovascular risk factors such as elevated plasma triglycerides, decreases high-density lipoprotein cholesterol and causes hyperglycemia." (PMID 23721527, 2013). "Telomere length has been linked to insulin resistance and our findings of insulin signaling as a key target that is upregulated progressively as the time of RR practice increases corroborates this association." (PMID 23650531, 2013). "Both insulin resistance and plasma insulin concentration are associated with muscle breakdown in non-diabetics." (PMID 23741490, 2013). "Plasma BCAAs and glutamine are increased in obesity and insulin resistance, but decrease after gastric bypass surgery resulting in weight loss and improved insulin sensitivity." (PMID 24225036, 2013). "It is clear that insulin resistance plays an early pathogenic role in the development of T2D, and defects in insulin secretion by pancreatic β cells are instrumental in the progression to hyperglycemia." (PMID 23221991, 2013). "Previous studies have shown that smoking reduces insulin sensitivity or induces insulin resistance and enhances cardiovascular risk factors such as elevated plasma triglycerides, decreases high-density lipoprotein cholesterol (HDL-C) and causes hyperglycemia." (PMID 23721527, 2013). "The hallmark of the theory linking insulin resistance to mitochondrial dysfunction is the accumulation of IMCL whose altered metabolism impairs insulin signaling." (PMID 23776659, 2013). "In both flies and mammals, peripheral insulin resistance is associated with a compensatory increase in production and secretion of insulin peptides." (PMID 23630454, 2013). "Since PCOS is associated with defects in insulin activation and β-cell pancreatic dysfunction, the interest in the molecular mechanisms underlying the insulin resistance in PCOS has increased." (PMID 23844380, 2013). "After GC treatment, a shift in energy metabolism from glucose to FFA, impaired insulin signaling transduction, and reduced glucose uptake into skeletal muscle have been associated with insulin resistance." (PMID 24312573, 2013). "Lipid deposits in muscle (intramyocellular lipids, IMCL) are associated with both insulin resistance and enhanced insulin sensitivity according to the athlete’s paradox proposed by Goodpaster." (PMID 23460866, 2013). "Adiponectin plays an important role as insulin-sensitizing adipokine which production is decreased in obesity and in conditions associated with insulin resistance." (PMID 23413782, 2013). "Insulin resistance (IR) and defects in islet β-cell insulin secretion are the main causes of impaired glucose tolerance (IGT) and overt type 2 diabetes in obese adults and adolescents." (PMID 24137224, 2013). "Diabetes mellitus is characterized by chronic hyperglycemia with disturbances of carbohydrate, fat and protein metabolism that result from deficiency of insulin secretion and/or insulin resistance." (PMID 23755289, 2013). "In conclusion, we show for the first time the association between COBLL1 rs7607980 C allele, lower insulin levels and lower insulin resistance in overweight and obese children." (PMID 23463496, 2013). "On the other hand, weight loss or insulin-sensitizing agents lead to increases in ADP levels in association with improved insulin resistance." (PMID 24145612, 2013).
Insulin resistance (continued). "A HOMA-IR >2.89 indicates insufficient compensation for insulin resistance, which suggests the need for a treatment aimed at improving susceptibility of tissues to insulin combined with insulin therapy." (PMID 23819910, 2013). "It is known that insulin resistance such as in obesity is associated with an increased insulin secretion." (PMID 23762879, 2013). "We examine if this derived measure of insulin sensitivity offers any advantage over HOMA-IR in identifying individuals with insulin resistance and risk of future cardio-metabolic events." (PMID 24098646, 2013). "49% of cases were insulin resistant respect to 34% of controls [OR 1.86], suggesting that insulin resistance can nearly double the risk of breast cancer development." (PMID 23497533, 2013). "In Chinese, the association of GCKR variants with glucose, insulin, insulin resistance and the risk of type 2 diabetes was inconsistent with Europeans." (PMID 23383164, 2013). "In this regard, our report provides important information in that a novel miRNA was identified that can explain the mechanism of insulin resistance in the muscle system; additionally, a new link associating insulin resistance to inflammation was discovered." (PMID 24349514, 2013). "In the study on the Canadian youth, factor analysis revealed that BMI/insulin/lipids, BMI/insulin/glucose, and blood pressure, with a unifying role for markers of insulin resistance and adiposity, underlie the MetS." (PMID 23476647, 2013). "An improvement in insulin sensitivity was observed in animal model of FFA-induced insulin resistance when the gene encoding for TLR4 was mutated." (PMID 23835113, 2013). "Elevated C3 concentrations were associated with increased risk of impaired insulin sensitivity, insulin resistance, abdominal obesity and low HDL cholesterol compared to low C3 concentrations." (PMID 23552612, 2013). "Chronic hyperglycemia is a cause of impaired insulin biosynthesis and secretion, the progression of which causes insulin resistance and is often accompanied by β-cell degranulation and apoptosis." (PMID 24324490, 2013). "Because DAG accumulation is associated with insulin resistance in rodents, it is likely responsible for the development of blunted adipose insulin signaling in seals." (PMID 23997935, 2013). "Chronic hyperglycemia-mediated oxidative stress and insulin resistance associated abnormity in insulin/insulin receptor signal pathway are the focus in the current researches." (PMID 24386004, 2013). "Hypoxia induces insulin resistance in murine 3T3L1 adipocytes and adipose tissue hypoxia is associated with obesity and systemic insulin resistance in in vivo murine systems." (PMID 23967162, 2013). "New-onset diabetes mellitus is a form of type 2 diabetes, which is thought to develop in response to a relative insulin deficiency resulting from increased insulin resistance or impaired insulin production." (PMID 23762090, 2013). "The observed insulin resistance of female and male Nur77-deficient mice is consistent to the tendency of increased fasting insulin levels in Nur77 deficient mice." (PMID 23342015, 2013). "More recently, TCF7L2 rs7903146 was associated with increased MetS risk, arising from their impaired insulin sensitivity, greater insulin resistance, increased abdominal obesity and hypertension." (PMID 23306188, 2013). "Metabolomics studies in humans have shown that BCAA-related metabolites are strongly associated with insulin resistance, and can be predictive of improvement in insulin sensitivity with intervention." (PMID 24339975, 2013). "It is well established that insulin resistance associated with a progressive decrement in insulin action occurs with aging." (PMID 23442260, 2013). "Hepatic steatosis (fatty liver) is associated with hepatic insulin resistance, characterized by decreased suppression of hepatic glucose production and lower insulin-stimulated liver glycogen synthesis." (PMID 23401754, 2013).
Insulin resistance (continued). "Rather, it is associated with a worsening of insulin resistance and an inappropriately low insulin response." (PMID 24151517, 2013). "Whereas low circulating ghrelin has been associated with elevated fasting insulin and insulin resistance in humans, the opposite is true for RBP4." (PMID 23840311, 2013). "Adiponectin is the most abundant adipose-specific protein, and it plays an important role as an insulin-sensitizing adipokine whose production is decreased in obesity and in conditions associated within insulin resistance." (PMID 23876229, 2013). "Oxidative stress is a main inducer of insulin resistance; thus, although the precise mechanisms are not completely understood, Nrf2 is associated with insulin signaling pathway and insulin resistance." (PMID 24194976, 2013). "In their study, the first PC (mostly medium- to long-chain ACs) was associated with improved insulin sensitivity and the second PC (mostly AAs and short-chain ACs) was associated with an increase in insulin resistance." (PMID 24330454, 2013). "Sarasota Bay dolphins had lower postprandial insulin, glucose, triglycerides, cholesterol, and liver enzymes, supporting that Sarasota Bay dolphins have a lower risk of insulin resistance and metabolic syndrome." (PMID 24133483, 2013). "Future pharmaceutical interventions aimed at improving adipose tissue function in various subcutaneous depots have potential to help maintain adequate insulin sensitivity and reduce risk for development of insulin resistance complications." (PMID 23691287, 2013). "Liver steatosis is associated with both hepatic and adipose tissue insulin resistance, as well as reduced systemic insulin sensitivity." (PMID 24152749, 2013). "Subjects classified with metabolic syndrome were more insulin resistant, which was fully anticipated since insulin resistance is thought to be the core defect underlying this condition." (PMID 24358323, 2013). "It is well established that insulin resistance, reflected in increased plasma insulin levels, is an underlying feature of abdominal obesity, and a major component of the metabolic syndrome." (PMID 24533222, 2013). "T2D develops in adulthood and is generally considered to be a condition marked by insulin resistance and loss of function of insulin-secreting pancreatic beta cells." (PMID 23849268, 2013). "Both aging and physical inactivity are associated with increased development of insulin resistance whereas physical activity has been shown to promote increased insulin sensitivity." (PMID 23805253, 2013). "In our research, we found that the Spleen Qi deficiency group had higher fasting blood glucose (FBG), insulin, greater insulin resistance, and higher HbA1c than the Qi and Yin deficiency group." (PMID 23762155, 2013). "Discussion: Recent studies specifically designed to investigate the effect of pollutants on insulin sensitivity show a potential causation of insulin resistance." (PMID 24058052, 2013). "Subjects with the GG genotype for rs9997745 SNP had increased MetS risk (OR 1.90), displayed elevated fasting glucose and insulin concentrations and increased insulin resistance compared with subjects carrying the A allele." (PMID 23306188, 2013). "Insulin resistance (IR) refers to a state in which a given concentration of insulin is associated with a subnormal glucose response." (PMID 23339356, 2013). "In vivo rs2295490 has been associated with insulin resistance, defective insulin secretion, T2D, and CVD." (PMID 23762820, 2013). "PP2A has been associated with control of the major serine-threonine kinases in growth and signaling and as such has long been implicated in insulin signaling and the onset of insulin resistance." (PMID 23840384, 2013). "As insulin has pleiotropic functions, insulin resistance is closely linked with other metabolic symptoms such as hypertension and hyperlipidemia." (PMID 23781214, 2013).
Insulin resistance (continued). "Insulin resistance has a central role in the pathogenesis of diabetic dyslipidemia which causes increased free fatty-acid release from insulin-resistant fat cells and promotes more triglycerides production." (PMID 23936668, 2013). "In fact, main feature of MetS is attributed to insulin resistance, and weight loss seems to play an indirect role by increasing insulin sensitivity." (PMID 23819128, 2013). "Inflammation plays a causal role in insulin resistance, and in rodent models targeting inflammatory cytokine production through genetic and pharmacological approaches results in improvements in insulin signaling." (PMID 23483669, 2013). "Taken together, the present results indicate that reduced GLP-1 secretory function is associated with insulin resistance and post-prandial hyperglycemia even before insulin secretion is compromised." (PMID 23844037, 2013). "Insulin resistance in women of African ancestry is associated with an appropriately greater insulin response to maintain normoglycemia." (PMID 23401754, 2013). "Here, increased IMCLs were associated with altered expression of key regulators of insulin signaling and glucose metabolism, which can lead to insulin resistance in association with mitochondrial dysfunction." (PMID 24098655, 2013). "Thiamine deficiency leaded to impaired insulin synthesis and secretion and ultimately the development of insulin resistance (IR) and macrovascular disease." (PMID 23898830, 2013). "TNF-α has been implicated in the progression of insulin resistance; it disrupts phosphorylation of several proteins involved in insulin-signalling pathway, including IRS1, tyrosine, and most importantly, the downregulation of glucose transporter 4 (GLUT4)." (PMID 24391675, 2013). "Hypereosinophilic mice displayed improved insulin sensitivity, while eosinophil-deficient mice exhibited increased fat together with impaired glucose tolerance and insulin resistance." (PMID 23964268, 2013). "In conditions where prolonged elevation of glucose causes hyperinsulinemia (as associated with insulin resistance) in the bloodstream, a reduction of insulin crossing the blood brain barrier can occur." (PMID 24358323, 2013). "Pro-inflammatory cytokines released by activated immune cells and adipocytes can impair insulin signaling in insulin-responsive organs, promoting systemic insulin resistance, which increases the risk of developing type 2 diabetes (T2D)." (PMID 24416031, 2013). "Leptin directly inhibits insulin secretion from pancreatic β-cells and elevated serum leptin levels are associated with fasting insulin, insulin resistance (HOMA-IR), and total cholesterol, the core metabolic disturbances of the metabolic syndrome." (PMID 24455217, 2013). "Levels of fasting blood glucose (FBG), insulin, leptin, and leptin receptors were measured by enzyme linked immunosorbent assay (ELISA), and homeostasis model assessment of insulin resistance (HOMA-IR) was calculated." (PMID 24102053, 2013). "This study, along with recent data of in vitro DRG insulin resistance, strongly supports altered insulin signaling as a pathogenic mechanism in DN." (PMID 24252636, 2013). "Previous studies have demonstrated that insulin resistance in patients with HIV-LD are associated with decreased insulin-stimulated glycogen synthase (GS) activity." (PMID 23533568, 2013). "Primary is associated with insulin resistance and metabolic derangements, and secondary is associated with non-insulin related conditions." (PMID 24152749, 2013). "Both factors contribute to insulin resistance and loss of β-cell function that result in impairment in insulin action, insulin production, or both." (PMID 23662132, 2013). "Type 2 results from the ineffective use of insulin due to insulin resistance and deficient glucose metabolism." (PMID 24348714, 2013). "This protocol can improve insulin sensitivity and minimize the damage caused by insulin resistance in obese individuals." (PMID 23496920, 2013).